GZMB (granzyme B)
Diseases named in the same sentence as GZMB in open-access papers (continued):
Sharing a sentence is not in itself a finding about the gene and the disease.
tumor (continued). "Furthermore, NK cells kill tumour cells by releasing cytolytic granules such as granzyme B, which induce apoptosis in tumour cells." (PMID 33399495, 2021). "As for how CD8+ T cells may kill the tumor cells, the perforin/granzyme-B apoptosis pathway is a likely candidate, but there are also reports that T cell-promoted tumor ferroptosis is an anti-tumor mechanism, which needs further exploration." (PMID 34054811, 2021). "Moreover, immunohistochemistry (IHC) analysis indicated that biomarkers for T‐cell activation (including CD3, CD8, and granzyme B) detected on tumor cells of mice exposed to ethanol were remarkably lower than those in control mice." (PMID 34026438, 2021). "NK cells can directly kill tumor cells by secreting perforin, granzyme B, and cytokines." (PMID 34113342, 2021). "Upon binding and uptake, granzyme B induces apoptosis selectively in tumor cells." (PMID 34905138, 2021). "Moreover, univariate survival analysis indicated that CD4+ GzmB+ T cells infiltration levels in the central area of the tumor positively correlated with the patient’s OS and DFS." (PMID 34631551, 2021). "Among them, granzyme B+ CD8+ cytotoxic T cells (CD8_4) had significantly more interactions with multiple tumor cell subtypes (tu_1, tu_2, tu_3, and tu_5) in LTS than in STS, suggesting increased interactions between CD8 cytotoxic cells and multiple subtypes of tumor cells in LTS." (PMID 33917869, 2021). "Treg from tumor tissues had eight specific pathways including coronavirus pathogenesis, granzyme B, cell cycle control, Natural killer cell, cholesterol biosynthesis III, superpathway of cholesterol biosynthesis, cholesterol biosynthesis II and cholesterol biosynthesis I." (PMID 34084175, 2021). "Nonetheless, the reason why tumor cells evolved to produce granzyme B, which might lead to their suicide, is still unknown." (PMID 33868318, 2021). "Importantly, doxorubicin increased the numbers of CD4+ and CD8+ T cells, effector T cells, and NK cells and the expression of IFN-γ, granzyme B, and perforin in tumor-bearing mice." (PMID 34638242, 2021). "Granzyme B is a major cytotoxic protein that drives cytotoxic T-cell-mediated tumor cell killing." (PMID 34832863, 2021). "To substantiate the ability of the analysis pipeline for spatial subanatomical expression analysis, we sought to analyze the effect of tumor antigen expression on the spatial expression of effector gene GZMB and IFNγ and the spatial datasets were divided into a CD19high and CD19low area." (PMID 34155235, 2021). "Moreover, CD69+CD103+CD8+ T cells from anti-PD-1-treated B16F10E-KO tumours expressed more frequently granzyme B than isotype-treated B16F10E-KO." (PMID 34471106, 2021). "It is generally known that after CD8+ T cells recognize the antigen, degranulation leads to the release of perforin, which promotes the formation of pores on the tumor cell membrane, allowing granzyme B to enter the cytoplasm to activate the pro-apoptotic Bcl-2 family members." (PMID 33477737, 2021). "Of note, when discriminating between the intra-tumoral and peri-tumoral regions, only the percentage of CD8 + Granzyme B+ T lymphocytes within the tumor masses retained the prognostic value, supporting the importance of effector cell localization in metastatic UM." (PMID 33947438, 2021). "Moreover, cisplatin can sensitize tumor cells to granzyme B by augmenting tumor cell permeability and by increasing the expression of the granzyme-target caspase-3, which mediates the execution phase of apoptosis." (PMID 34712615, 2021). "NK cells can then kill tumor cells in an NKG2D-dependent way or by increasing granzyme B release." (PMID 34572948, 2021). "Furthermore, use of anti-PVRIG mAb also enhanced the cytotoxic potential of tumor-infiltrating NK cells, indicated by higher expression of CD107a and GzmB." (PMID 34174928, 2021).
tumor (continued). "Significant differences in frequencies of granzyme B+ cells within the CD8+ T cell subset were also not detected between tumor associated cells and PBMC for each patient." (PMID 34926643, 2021). "Moreover, Hsp70 is involved in the granzyme B-dependent cytolysis of tumor cells under the effect of NK cells." (PMID 34206968, 2021). "Another important distinction was the tumor-associated presence (2% of CD3+ T cells) of Lag3+ Granzyme B+ cytotoxic T cells (“TcEFF_II”) within the liver but not in the lung microenvironment." (PMID 33985562, 2021). "TIM-3 could also inhibit the killing effect of Vγ9Vδ2 T cells on tumor by reducing the expression of perforin and granzyme B. PD-1 and TIM-3 antibodies could protect anti-tumor activity of Vγ9Vδ2 T cells." (PMID 33664732, 2020). "Moreover, the NK cells that remained at the tumor site showed lower levels of cytolytic activity, as these cells expressed similar levels of IFNγ and lower levels of granzyme B compared to those in peripheral blood." (PMID 32117733, 2020). "An “immune hot” TIME exhibited tumor infiltration of granzyme B+CD8+ T cells (GzmB+CD8+ T cells), a type 1 IFN signature, and elevated expression of multiple immune inhibitory molecules, including indoleamine 2,3-dioxygenase (IDO) and PD-L1, was associated with good outcomes." (PMID 32486021, 2020). "In the K7M2 osteosarcoma model, IL-18 seems to be implicated in MDSC recruitment at the tumor site and the association of anti-PD-1 with IL-18BP (an inhibitor of IL-18) increases the proportion of CD8+ IFNγ+ GzmB+ T cell tumor infiltration, and decreases tumor weight." (PMID 33261061, 2020). "Similar to Vγ9Vδ2 T cells, Vδ1 T cells could kill tumor cells through the perforin-granzyme B, Fas/FasL and TRAIL pathway." (PMID 33664732, 2020). "We could show that Hsp70-targeting NK cells are capable to specifically recognize and kill tumor cells presenting Hsp70 on their plasma membrane most likely via granzyme B mediated apoptosis." (PMID 32276468, 2020). "However, it is suggested that the rapid cell death pathway mediated through Perforin and Granzyme B is the major one responsible for tumor cell killing." (PMID 32185408, 2020). "Activated basophils release mediators, such as granzyme B, TNFα and histamine, which may act directly to regulate tumor growth." (PMID 32645919, 2020). "Furthermore, NK cells present in the tumor of Caspase-1-deficient hosts expressed higher levels of NK cell activation markers NKG2D, Granzyme B (GZB), CD69 and CD98." (PMID 33042810, 2020). "Further studies will be needed to elucidate other factors affecting the interpretation of granzyme B targeting tracers before they could be used for stratification of patient response across multiple tumour phenotypes." (PMID 32705455, 2020). "In addition, we observed that the tumor-infiltrated OT1-iT cells (CD45.2+CD8+) secreted interferon gamma (IFNγ) and granzyme B (GzmB), which indicated their tumor cell killing behavior." (PMID 32669292, 2020). "In PDA animal models, we identified that either engineered or endogenous intratumoral tumor antigen-specific T cells also become defective in their production of IFNγ, TNFα and expression of cytolytic molecules including Granzyme B following specific peptide recognition." (PMID 33584701, 2020). "Th9 cells can also kill tumor cells directly by secreting granzyme B in some tumors." (PMID 32228589, 2020). "In addition, the increased expression of IFNγ and granzyme B, as well as a three-fold increase in tumor-infiltrating CTLs, was observed." (PMID 32224883, 2020). "Recent studies showed that the single A2AR blockade or the combination with either PD-1/PD-L1 or CTLA-4 mAbs induces T-cell proliferation, enhances the expression of IFNγ and granzyme B by tumor-infiltrating CD8+ T-cells, thus restraining the tumor growth in preclinical models." (PMID 32760402, 2020). "Cytotoxic function of the tumor microenvironment was assessed by granzyme B staining." (PMID 31911474, 2020).
tumor (continued). "Apoptosis can be initiated via death receptor ligation, FasL and TRAIL, but also by secreting perforin and granzyme B. To avoid CTL-mediated killing, tumor cells down-regulate MHC class I but also undergo mutations that reduces the antigen processing and presenting capacity." (PMID 32499786, 2020). "Upon tumor contact, NK cells start to mobilize perforins and GzmB towards the tumor cells." (PMID 33552053, 2020). "Consistent with the report of granzyme B’s being a useful predictive imaging biomarker for immunotherapy, our data showed that granzyme B expression negatively correlated with tumor weight, with an exponential increase in weight with decreasing granzyme B expression." (PMID 31911474, 2020). "This is a representative IF figure for the markers cytokeratin, PD-L1, CD4, CD8, perforin and granzyme B. Image analysis of IF staining of tumor sections revealed enhanced CD4 T cells, CD8 T cells, perforin and granzyme B but reduced tumor-specific cytokeratin following therapy." (PMID 33167311, 2020). "Results obtained in this work led us to propose that a similar mechanism of cytoprotection elicited by autophagy could be responsible for impaired elimination of tumor cells by CTLs, such as granzyme B and perforin that are also present in CTLs." (PMID 33117715, 2020). "As postulated, the addition of BCL-2 inhibitors may sensitize the target tumor cells to perforin/granzyme-B mediated cell kill." (PMID 32131385, 2020). "In line with this, GZMB expression has been suggested to promote tumor immunoevasion, favoring B regulatory (Breg) and T regulatory (Treg)-mediated immune suppression, dampening antitumor NK cell and T lymphocyte responses, albeit contradictory results that have been obtained to date." (PMID 32466293, 2020). "II of CD8 T cells producing granzyme B (GZMB) depending on the tumour grade." (PMID 32277125, 2020). "Moreover, iNKT cells have the ability to kill CD1d-expressing tumor cells directly via the perforin/granzyme B, Fas-Fas ligand system and tumor necrosis factor-α-related apoptosis-inducing ligand (TRAIL)." (PMID 32973759, 2020). "Glioma cells deficient for galectin-1 showed reduced tumor growth, increased intra-tumor NK cell infiltration, and elevated expression of granzyme B when implanted into the striatum of Rag1−/− mice (which develop NK, but not T or B cells) when compared to Rag1−/− mice injected with wild-type cells." (PMID 32063906, 2020). "γδ T cells recognize tumor cells and release perforin and granzyme B into the synaptic space." (PMID 33664732, 2020). "Granzyme B production within the tumor microenvironment of the AA+anti-PD1 group (0.4 ± 0.06%) was significantly higher than AA alone (0.18 ± 0.07%, t test, P = 0.02), anti-PD1 alone (0.18 ± 0.03%, t test, P = 0.004), and vehicle (0.09 ± 0.015%, t test, P < 0.001)." (PMID 31911474, 2020). "Furthermore, these altered M2-like macrophages were able to cause a significant increase in the levels of IFNγ produced from co-cultured CD4+ T cells, and also significantly increased granzyme B release from CD8+ T cells in response to tumor cells." (PMID 32455916, 2020). "Another study showed that stimulation of the reward system through dopaminergic neurons in ventral tegmental area decreased tumor growth in mouse models by reducing myeloid-derived suppressor cells and increasing granzyme-B expression in tumor-infiltrating CD8+T cells." (PMID 32973771, 2020). "Notably, granzyme B expression levels were similar between AAmut and AOD tumor sites, whereas granzyme B expression level was significantly lower in the AOD samples than in the peripheral blood samples (p < 0.05)." (PMID 33614475, 2020). "These cells adhere to the epithelial cells via the interaction of CD103 with epithelial E-cadherin and can directly lyse epithelial tumor cells by releasing lytic granules such as granzyme B upon epithelial E-cadherin and CD103 interaction, thus helping to maintain epithelial integrity." (PMID 31933142, 2020).
tumor (continued). "Moreover, in patients with renal carcinoma, activated Vγ9Vδ2 T cells showed a strong cytotoxicity to autologous tumor cells through perforin and granzyme B." (PMID 33664732, 2020). "Thus IL-2 is critical for GzmB expression by endogenous tumor-infiltrating CD4+ T cells with little impact on other features of CD4+ T cell activation and differentiation in response to αCTLA-4." (PMID 31924474, 2020). "Granzyme B+ cells were found to be significantly higher in IM and CT of T1-T2 stage tumors compared to T3-T4 tumors suggesting that small tumor size may be attributed to Granzyme B mediated killing of tumor cells." (PMID 33211709, 2020). "Cytotoxic T cells can kill tumor cells directly and their cytotoxicity is mediated through several pathways, including release of granulae containing the cytotoxic proteins Perforin and Granzyme B or the expression of Fas-L." (PMID 32185408, 2020). "Furthermore, a significant increase in the ratio of GzmB+CD4+Foxp3− to CD4+ Foxp3+ cells was also observed post-treatment, suggesting an inverse relationship between Treg cell frequency and GzmB expression in tumor-infiltrating CD4+ T cells." (PMID 31924474, 2020). "Furthermore, granzyme B has a prominent cytotoxic role in mediating cancer cell death, an anti-tumor activity that correlates with response to ICI therapy." (PMID 32998446, 2020). "The cytotoxicity induced by the immunological synapse thus created is due to T-cell release of two cytolytic-initiating proteins—perforin, which produces transmembrane pores in the tumor cell and granzyme B, which navigates through the created pores to initiate apoptosis in the tumor cells." (PMID 32707894, 2020). "However, if autophagy is blocked by deletion of BECN1, granzyme B levels are restored and favors tumor regression in vivo due to tumor cell death by NK-mediated lysis." (PMID 33324568, 2020). "Moreover, cryo-thermal therapy improved the cytolytic activity of eosinophils, as demonstrated by the up-regulation of cytotoxic molecules (e.g. granzyme-B and perforin), and enhanced tumour-killing capacity on tumour cells." (PMID 31519961, 2019). "Moreover, CD8+ TIL from mice treated i.p. with anti-Nrp-1 plus anti-PD-1 expressed higher levels of granzyme B and mediated stronger cytotoxic activity toward autologous MC-38 tumour cells than TIL from mice treated with each mAb alone." (PMID 31350404, 2019). "Type 1 ILCs are characterized by particular surface markers such as CD127- and CD49a+ and by their ability to produce granzyme B. These type 1 ILCs expanded in mouse mammary pre-cancerous lesions and they exhibited potent cytotoxic activities against tumor cells, limiting tumor growth." (PMID 31024531, 2019). "Taken together, CD8+NKT-like cells could exert NK- and CTL-like antitumor effects through the elimination of both tumor cells and MDSCs in a granzyme B-dependent manner." (PMID 31278476, 2019). "In addition, CT treatment also elevated the expression of granzyme B, perforin, and IFNγ in the tumors, thus, demonstrating CT promotion of a Th1-polarized tumor microenvironment critical for combatting tumors." (PMID 30972427, 2019). "When stimulated with T-cell receptor activator, tumor-infiltrating NKG2A+ CD8+ T cells could secrete large amounts of granzyme B." (PMID 32010126, 2019). "Moreover, expression of PD-L1 and the cell proliferation marker Ki67 in the tumours decreased and levels of secreted granzyme B by modified CAR T cells increased." (PMID 30413825, 2019). "Indeed, under ideal circumstances, DCs take up tumor antigens and promote the generation of anti-tumor specific T cells, which ultimately infiltrate the tumor bed and kill their target cells through cytolytic mechanisms (i.e., perforin and granzyme B)." (PMID 31649669, 2019). "Additionally, the high expression of granzyme B and FasL in cytotoxic cells of the tumor microenvironment was obviously observed in the combination‐treated mice." (PMID 31380170, 2019).
tumor (continued). "In vitro blocking experiments showed that granzyme B inhibitor efficiently suppressed the cytotoxicity of CD8+NKT-like cells against tumor cells and MDSCs, while Fas ligand (FasL) or tumor necrosis factor-related apoptosis-inducing ligand (TRAIL) inhibition failed to produce similar effects." (PMID 31278476, 2019). "Moreover, hypoxic tumor cells take advantage of the induction of autophagy to selectively degrade the serine protease granzyme B (GZMB) released by NK cells." (PMID 31540045, 2019). "Indeed, CLSM observations showed substantial polarization of granzyme-B and cationic proteins in IL-33 EO-tumor cell conjugates." (PMID 31717819, 2019). "Tumour infiltrating CD8+ T cells isolated at 3 weeks also express less Granzyme B and perforin." (PMID 31277636, 2019). "Detailed analyses of adoptively transferred CD4+ T cells during tumor challenge revealed the expression of granzyme B, FasL, TNF-α, and IFN-γ in such T cells that might be involved in the antitumour activity." (PMID 31183361, 2019). "Next, we detected the expression of effector molecules in tumour-infiltrating NK cells and found that the expression of granzyme B was decreased in comparison with that in adjacent tissues or peripheral blood, but perforin expression was not significantly changed." (PMID 31324197, 2019). "The release of granzyme B a definite indicator of anti-tumour T-cell function, and has been targeted for PET imaging during immunotherapy 98, 99 with the aim to increase specificity in the detection of effective immune responses, rather than increased presence of T-cells." (PMID 31656546, 2019). "In 4 T1 tumor models, the accumulation of exosomal PD-L1 in the tumor microenvironment induced immunotherapy resistance by suppressing the secretion of granzyme B. Notably, knockdown of Rab27a in tumor cells significantly enhanced the efficiency of anti-PD-1 therapy and inhibited 4 T1 tumor growth." (PMID 31647023, 2019). "Furthermore, we found that granzyme B expression in tumour-infiltrating NK cells was decreased in comparison with that in adjacent tissues and peripheral blood, indicating impaired cytotoxicity." (PMID 31324197, 2019). "The flow cytometry showed that tumor- and spleen-MDSCs expressed perforin and GzmB." (PMID 31212684, 2019). "Indeed, VD-supplemented mice exhibited higher Granzyme B and PD-1 expression levels in tumor infiltrating CD8+ T cells (1.3 and 1.4-fold, respectively) as compared with control mice." (PMID 31244851, 2019). "Moreover, Kctd9-depleted NK cells displayed insufficient IFN-γ production, degranulation, and granzyme B production in response to cytokine stimulation, and attenuated cytotoxicity to tumor cells in vitro." (PMID 31024568, 2019). "In addition, we tested cell death in those tumor tissues by analyzing Granzyme B+/CD8+ and perforin+/CD8+ population using flow cytometry." (PMID 30948928, 2019). "To explore the immune response against tumors in CRC model mice, we performed immunohistochemical analysis (IHC) to analyze the Foxp3, CD8, and Granzyme B expression after therapy; this was quantified as the number of positive cells divided by total cells in the tumor microenvironment." (PMID 31882868, 2019). "This prompted us to quantify cytotoxic (granzyme B+) T cells in TNFα‐CSG‐treated 4T1 tumours." (PMID 31709774, 2019). "Instead, in a study with murine hypodense eosinophils tumor apoptosis was mediated by granzyme-B." (PMID 31717819, 2019). "NKG2D and granzyme B were highly upregulated in tumor infirtrating CD8 T cells." (PMID 31307539, 2019). "Interestingly, our results indicated that sorted CD8+ cytotoxic Tcells expressed remarkably high levels of granzyme B and perforin indicating a high tumor cell-killing potential." (PMID 30979375, 2019).